CD44 (CD44 molecule (IN blood group))
Diseases named in the same sentence as CD44 in open-access papers (continued):
Sharing a sentence is not in itself a finding about the gene and the disease.
COVID-19 (continued). "As low CD44 expression is associated with increased neutrophil migration to the lungs, it may be that pulmonary infiltration of LDIBs contributes to the “progenitor” phenotype of neutrophils detected in the BALF samples of critical COVID-19 patients." (PMID 34149717, 2021). "None of the other measured mediators related to eosinophils and the T2 response (CCL26, IL-3, IL-4, IL-5, CD44, TSLP, or GM-CSF) displayed any significant differences between the different timepoints and between COVID-19 versus controls." (PMID 40710346, 2025). "Studies also show that CD44 is highly expressed in CD4+ and CD8+ T cells of severe COVID-19 patients, which further supports the interconnected relationships these proteins have within the immunological response to COVID-19." (PMID 39334929, 2024). "High levels of HA in the plasma of COVID-19 patients have been shown to directly induce endothelial barrier dysfunction in a ROCK- and CD44-dependent manner, indicating a role for HA in the vascular pathology of COVID-19." (PMID 36851616, 2023). "In support of our findings, lymphocyte activation markers such as CD38, CD69, and CD44 are highly expressed on CD4+ and CD8+ T cells of COVID-19 patients, and CD73 absence in CD8+ T cells induces granzyme production in these individuals." (PMID 36248842, 2022). "The relative MFIs of CD69 and CD44 in CD4+ T cells, CD8+ T cells, and NK cells were significantly lower in RTP patients than in patients with moderate COVID-19 and severe COVID-19." (PMID 34687295, 2021). "Gal-9 via interaction with CD44 requires synergistic effects of TGF-β to enforce induced Treg differentiation, which is less likely to occur in COVID-19 patients with significant downregulation of TGF-β levels." (PMID 33947753, 2021). "CD8+ T cells from COVID-19 patients have a very marked activation phenotype with an increase in CD69, CD38, CD137, and CD44, especially in critically ill patients." (PMID 33193331, 2020). "These CD4+ T-cells in COVID-19 patients have higher expression of CD69, CD38 and CD44 compared with healthy controls, indicating their activated status." (PMID 34676125, 2020). "CD8+ T-cells in COVID-19 patients also showed activated phenotypes with higher expression of CD69, CD38 and CD44." (PMID 34676125, 2020). "We quantified the area covered by CD44 and again found no significant increase in CD44 labeling in the COVID-19 ION." (PMID 37483351, 2023). "Finally, we show that HA fragments present at high levels in COVID-19 patient plasma can directly induce endothelial barrier dysfunction in a ROCK- and CD44-dependent manner, indicating a role for HA in the vascular pathology of COVID-19." (PMID 34314391, 2021). "Notably, CD44, previously reported to regulate the TLR2-mediated macrophage activation and proinflammatory responses, was also found to be significantly increased in ROIs in islet, ductal, and exocrine areas of COVID-19 samples." (PMID 39232561, 2024). "However, unlike what is typically seen with activated mature blood eosinophils, we found here increased CD125 and CD63, a reduction in CD44, and a lack of change for HLA-DR and CRTH2 in COVID-19." (PMID 40710346, 2025). "In addition, the blood eosinophil phenotype in COVID-19 did not correspond either to a tissue eosinophil phenotype, such as in allergic asthma where activated airway eosinophils displayed a very low amount of surface CD125 and high amounts of CD44." (PMID 40710346, 2025).
lung fibrosis (29 papers, 2012 to 2025). "In lung epithelial cells, TM4SF5 expression leads to suppression of ZEB2, which in turn increases alternative splicing factors for CD44 isoforms (from the standard CD44 form to CD44v8-10 variant form) during idiopathic pulmonary fibrosis." (PMID 34921636, 2021). "Instead, HA and CD44 seem to be important for the pro-fibrotic phenotype of recruited fibroblasts as genetic deficiency or pharmacologic inhibition of CD44 reduced the aggressive phenotype and pulmonary fibrosis, though pulmonary inflammation was increased." (PMID 28836991, 2017). "LFA-1 has also been linked to cell signaling properties with various hyaluronan receptors, including the toll-like receptors (TLR2 and TLR4) and CD-44, which have been linked to the pathogenesis of interstitial pulmonary fibrosis." (PMID 25324695, 2014). "Moreover, CD44 contributed to the progressive fibrotic phenotype because lung fibrosis was reduced by either crossing the α-SMA-HAS2 transgenic mouse with the CD44 deficient mouse or by treatment with a blocking antibody to CD44." (PMID 26448760, 2015). "For example, Cd44 knockout mice are protected against bleomycin-induced lung fibrosis as well as against myocardial fibrotic remodeling induced by chronic angiotensin II exposure." (PMID 41009438, 2025). "In models of renal, hepatic, and pulmonary fibrosis, the use of 4-methylumbelliferone (4-MU)—an inhibitor of HA synthesis—led to a reduction in its deposition in the tissue and indirect quenching of CD44 signaling." (PMID 41009438, 2025). "In a mouse model of bleomycin-induced lung fibrosis, a CD44-blocking Ab ameliorated lung injury in vivo." (PMID 39872532, 2024). "Honokiol can inhibit TGF-β/Smad signaling, matrix proteins, and the IL-6/CD44/STAT3 axis to reduce pulmonary fibrosis, which exerts anti-inflammatory and antioxidant effects." (PMID 36588723, 2022). "Intriguingly, CD44 has been shown to play a role in the development of pulmonary fibrosis as a regulator of fibroblast invasion." (PMID 32636398, 2020). "In our model CD44 kinetics in lung myofibroblasts is in good correlation with BLM-induced pulmonary fibrosis kinetics, which in young mice reaches maximum by day 14–21 and then regenerate the pulmonary tissue by day 28–56." (PMID 31591327, 2019). "On the other hand, in a model of pulmonary fibrosis, CD44 KO mice demonstrated enhanced and unresolved inflammation following intratracheal administration of bleomycin." (PMID 26999446, 2016). "In pulmonary fibrosis and hyperoxia induced lung injury models however, CD44 has a suppressive role on inflammation." (PMID 26999446, 2016). "CD44–HA signaling has been implicated in the progression of ILD, which includes idiopathic pulmonary fibrosis (IPF) and systemic sclerosis associated ILD." (PMID 25954275, 2015). "In this study, HAS2-overexpressing transgenic mice showed increased deposition of HA and accumulation and up-regulation of CD44 mRNA and protein in lung myofibroblasts after bleomycin-induced lung injury, resulting in increased lung fibrosis and fatality." (PMID 25954275, 2015). "We previously demonstrated that deposited CSPGs retained macrophages in fibrotic interstitium in a CD44-dependent manner in a bleomycin-induced pulmonary fibrosis model." (PMID 26646821, 2015). "CD44–HA signaling was shown to play a role in the development of progressive lung fibrosis by activation of myofibroblasts with an acquired invasive phenotype." (PMID 25954275, 2015). "The mechanism by which injected HA exerts CD44-dependent anti-fibrotic effects in murine OA appears related to the finding that the fibroblast to myofibroblast transition in progressive murine lung fibrosis is also modulated by HA in a CD44-dependent fashion." (PMID 22721434, 2012).
lung fibrosis (continued). "An analogy can be drawn to silicosis—just as silica dust induces lung fibrosis (silicosis) via CD44-dependent mechanisms, microplastics can induce “plasticosis,” characterized by chronic inflammation and scarring of organs (e.g., lungs, gastrointestinal tract) following the accumulation of plastics." (PMID 41009438, 2025). "To conclude, our results demonstrate the key role of CD44 in transdifferentiation and motility of AECs surviving stress induced by bleomycin and in subsequent suppression of lung tissue regeneration and promotion of pulmonary fibrosis." (PMID 31591327, 2019). "CD44-mediated signaling in pulmonary fibrosis has been addressed in a number of studies." (PMID 31591327, 2019). "Indeed, anti-CD44 treatment reduces fibroblast invasion and bleomycin-induced lung fibrosis, and inhibition of uPAR ligation significantly reduces motility of pulmonary fibroblasts from patients with idiopathic PF." (PMID 28330499, 2017). "For example, addition of exogenous HA of specific mass to isolated IPF fibroblasts may further elucidate the nature of CD44–HA signaling in progression of lung fibrosis." (PMID 25954275, 2015). "Treatment with a CD44-blocking antibody is shown to reduce lung fibrosis in mice." (PMID 24919189, 2014). "Considering the important role of macrophages in lung fibrosis progression and the high expression of CD44 on their surface, we analyzed whether liposomes would be internalized by the human monocytic leukemia cell line (THP-1 cells) differentiated toward macrophages lineage with PMA." (PMID 31509965, 2019). "These genes were identified in reports of the alternative splicing in pulmonary fibrosis of known etiologies CD44, RXFP1, and CD146, a pulmonary fibrosis mouse model (FGFR2), and a genetic link between COVID-19 and IPF (DP99 and ATP11A)." (PMID 39937013, 2025). "It was reported that the CD44, a putative receptor for CHI3L1, mediates invasive fibroblasts phenotypes leading to severe lung fibrosis." (PMID 35370755, 2022). "The invasive phenotype of fibroblasts isolated from patients with idiopathic pulmonary fibrosis was HAS2 and CD44 related." (PMID 35053193, 2021). "The cluster of differentiation 44 (CD44) antibody (IM7), dihydrotanshinone I (DHI) and verteporfin (VP) were used to explore the effect of CD44-RhoA-YAP signaling blockade on mechanics-induced fibroblast activation and CS-induced pulmonary fibrosis." (PMID 31410197, 2019). "In diseases such as idiopathic pulmonary fibrosis, where there are currently no effective drugs to reverse the scarring process, intervening in the CD44–HA interaction is a promising new strategy." (PMID 41009438, 2025). "In comparison to the neutrophilic cases, the IPA analysis of the proteomic datasets derived from horses with metachromatic inflammation revealed enrichment in pathways related to hypersensitivity reaction (CD44, ICAM1, SOD1, PSAP, CDH1) and lung fibrosis (AGER, TGFBR2, FBLN1, S100A9)." (PMID 39594673, 2024). "However, the specific roles of CD44, heparin-like molecules, and hyaluronic acid and their interactions with CHI3L1 in the pathogenesis of pulmonary fibrosis remain to be determined." (PMID 35370755, 2022). "Involvement of CD44 in EMT during pulmonary fibrosis as opposed to tissue regeneration (both in clinic and in experimental animals) is more scant." (PMID 31591327, 2019). "Progressive lung fibrosis requires fibroblast differentiation into an invasive myofibroblast phenotype, which is characterized by hyaluronan synthase 2 (HAS2) and CD44 expression and coordinated expression of matrix metalloproteinases (MMPs) and inhibitors of MMP functions." (PMID 29348826, 2017). "Importantly, the study showed that development of lung fibrosis in vivo was also dependent on HAS2 and CD44 expression." (PMID 26583132, 2015). "Thus, CD44 in BALF is a specific and reliable marker of pulmonary fibrosis." (PMID 39872532, 2024).
lung fibrosis (continued). "In vivo we found, for the first time that knocking out CD44, specifically in mesenchymal cells, excluding the hematopoietic lineage, leads to significantly improved outcome in the regenerative capacity of the tissue following bleomycin injury, particularly reducing EMT and pulmonary fibrosis." (PMID 31591327, 2019).
prostate tumor (29 papers, 2008 to 2025). "Orthotopic implantation with CD44+ cancer cells was associated with larger prostate tumors and more marked EMT changes in both male and castrated mice compared to CD44− cancer cells." (PMID 31315262, 2019). "To identifysuitable cancer cell lines for testing the binding affinity of LNPsmodified with AKPC, we measured CD44 expression levels in differentbreast and prostate tumor cells by Western blotting (WB)." (PMID 40176316, 2025). "We also observed that FKA inhibits Ubc12 neddylation, c-Myc, and keratin-8 expression in both CD44+/CD133+ prostate tumor spheroids and xenograft tumors." (PMID 35912174, 2022). "The orthotopic prostate tumors were probed with antibodies against NuMA, Lamin A + C, and CD44 or prostate-specific membrane antigen (PSMA), to distinguish between cells of human and murine origin." (PMID 34462519, 2021). "For instance, human prostate tumor cells with CD44+α2β1hiCD133+ phenotype represent potential PCSCs in vitro." (PMID 33816508, 2021). "A slightly higher toxicity was instead observed for CD44-positive prostate tumor cells, with a decrease in cell viability compared to untreated cells of ~ 30% for cells treated with bare AuNPs and ~ 35% for treatments with HA-capped NPs, respectively." (PMID 32349323, 2020). "Kalantari and coworkers have investigated CD133 and CD44 expression in a large set of prostate tumor tissues corresponding to various degrees of tumor progression." (PMID 31366128, 2019). "In summary, the present study demonstrates that miR-141, devoid in PCSCs, suppresses prostate tumour growth and metastasis by targeting a cohort of prometastasis genes including CD44, EZH2 and Rho GTPases." (PMID 28112170, 2017). "It was reported that CD44 positive cells from primary prostatic tumor tissues possess cell stemness." (PMID 27447616, 2016). "CD133 has been widely used, usually in combination with other stem cell markers such as CD44 and α2β1 integrin, to isolate cancer stem cells from prostate tumors with different Gleason grade, including cells from both primary and metastatic lesions." (PMID 27447616, 2016). "Tumorigenic or cancer stem cells that are typed CD133+CD44+CD49b+CD29+ have also been reported for prostate tumors." (PMID 21605402, 2011). "Each of the three different metastatic prostate tumor cell lines examined had remarkably high percentages of CD44 positively staining cells with each line staining for CD44 at greater than 95%." (PMID 24212937, 2011). "Furthermore, IHC data on 167 clinical prostate specimens demonstrated a positive correlation between CD44 and IL-6 levels in prostate tumor specimens." (PMID 31315262, 2019). "F77 can induce apoptosis on prostate tumor cell lines in a bivalent- and CD44-dependent manner." (PMID 29423071, 2018). "Collectively, numerous complimentary and cross-validating approaches we took in our studies deliver a clear message that miR-141 possesses prostate tumour and metastasis suppressive functions via targeting critical molecules including CD44, Rho GTPases and EZH2." (PMID 28112170, 2017). "Furthermore, EGCG inhibits the self-renewal capacity of CD44+α2β1+CD133+ CSCs isolated from human primary prostate tumors, as measured by spheroid formation in suspension." (PMID 20718984, 2010). "On top of that, T mutant allele of CD44 (rs8193C>T) could trigger PKC–Twist, PKC–Nanog, and Nanog–Stat signaling pathways through binding to PUM 2, which is related to prediction of prostate neoplasms and prognosis factor in prostate neoplasms." (PMID 38783892, 2024). "The CD44 (+), CD133 (+) cell subpopulations were isolated from human prostate tumors which exhibit stem-like properties showing therapeutic-resistance, capacity of self-renewal, and exact recapitulation of the original tumor in vivo." (PMID 30728896, 2019).
prostate tumor (continued). "To examine the role of CXCR4 in the cell adhesion and migration of prostate tumor initiating cells, we compared FACS sorted CD44+/CD133+/CXCR4+ cells with other populations in cell adhesion assays." (PMID 22359577, 2012). "By western blot analysis, we found that CK14, CD44, and CK8 markers were up-regulated in the prostate tumors as compared to the normal prostates." (PMID 21241512, 2011). "Thus, there is considerable similarity between breast and prostate tumour-initiating cells, and LNCaP CD44+CD24− cells provide a model system that may be useful in understanding the properties of these important tumour-initiating cells, whose underlying biology predicts poor clinical prognosis." (PMID 18268494, 2008). "Moreover, in human prostate tumor tissue, cells with low AR expression exhibit high STAT3 activity and coexpress CSC markers, including Nanog and CD44." (PMID 26880966, 2016). "Due to the heterogenic character of PCa cell lines, and the lack of universal markers for CSC in prostate tumors, generated spheres from all human and murine PCa cell lines were stained for an array of CSC markers including: CD44, SOX2, CD117 (c-kit), and CD49f." (PMID 30211124, 2018).